SERPINA5 (serpin family A member 5)
Diseases named in the same sentence as SERPINA5 in open-access papers (continued):
Sharing a sentence is not in itself a finding about the gene and the disease.
thyroid cancer (2 papers, 2013 to 2021). "We were unable to find any reports of changes in SERPINA5 expression in thyroid cancer, although several studies reported over-expression in SERPINA1 (belonging to the same gene cluster on human chromosome 14q32.1) in sporadic and radiation-related thyroid cancers." (PMID 23520464, 2013). "Moreover, there was no study on expression level of SERPINA5 in thyroid cancer, although some studies reported over-expression in SERPINA1 in sporadic and radiation-related thyroid cancers (Brenneret al., 2013; Sobhanet al., 2020)." (PMID 34837923, 2021).
Anxiety (1 paper, 2022). Intense feelings of nervousness, tension, or panic often arise in response to interpersonal stresses. "We found that SERPINA5 was a target gene of mmu-miR-3095-3p, which is associated with the anxiety-like behavior." (PMID 36699448, 2022). "SERPINA5 showed a target of mmu-miR-3095-3p, which was reported to be associated with anxiety-like behavior and microbiota, while IFNL3 was not." (PMID 36699448, 2022). "We searched the microbe-associated genes (IFNL3 and SERPINA5) to explore whether they interacted with miRNAs that were reported with depression/anxiety and microbiota." (PMID 36699448, 2022).
atherosclerosis (1 paper, 2022). A disease characterized by the build-up of fatty material and calcium deposition in the arterial wall resulting in partial or complete occlusion of the arterial lumen. "Finally, we found proteins related to atherosclerosis and aberrant hemostasis, including PRCP and SERPINA5." (PMID 35945262, 2022).
autoimmune thyroiditis (1 paper, 2013). "At the SNP level, the strongest associations were found for two SNPs in the SERPINA5 gene (rs6115 and rs6112), both of which persisted after FDR correction and were independent of history of autoimmune thyroiditis." (PMID 23520464, 2013).
chronic fatigue syndrome (1 paper, 2023). "A clinical study also demonstrated that SERPINA5 is associated with physical function in genetic chronic fatigue syndrome." (PMID 37525094, 2023).
colon cancer (1 paper, 2021). "Additionally, the expressions of SPARCL1, CP and TF differed significantly between stage IV colon cancer and normal (p < 0.05), while that of SPARCL1, CDH2, CP and SERPINA5 differed significantly between rectum adenocarcinoma and normal tissues." (PMID 34422629, 2021).
depression (1 paper, 2022). "Although the linkage between AD and PD was indicated, we found no results which suggested that SERPINA5 was associated with depression or gut microbiota." (PMID 36699448, 2022).
diabetes (1 paper, 2021). "Moreover, a 4-protein (SERPINA5, VPS4A, CP, TF) classifier was built to predict early stage DKD3 from diabetes." (PMID 34963468, 2021). "After performing the dimension reduction from the 24 overlapping DEPs from discovery and validation datasets, a 4-protein classifier (SERPINA5, VPS4A, CP, TF) could distinguish diabetes from DKD3." (PMID 34963468, 2021).
gastric cancer (1 paper, 2022). A primary or metastatic malignant neoplasm involving the stomach. "However, few report of SERPINA5 in gastric cancer has been found." (PMID 36000536, 2022).
glioblastoma (1 paper, 2020). The most malignant astrocytic tumor (WHO grade IV). "Among genes whose high expression correlates with decreased survival in glioblastoma, we identified several components of the “matrisome” and associated factors (FAM20C, SEMA3F, ADAMTSL4, ADAMTS14, SERPINA5, and CRELD1)." (PMID 32488114, 2020).
gout (1 paper, 2025). A condition characterized by painful swelling of the joints, which is caused by deposition of urate crystals. "Similarly, increased anticoagulant regulator SERPINA5 and decreased coagulation factor F12 suggest a shift in coagulation dynamics, which may contribute to the pro-thrombotic state reported in gout patients." (PMID 41511324, 2025).
HIV-1 infection (1 paper, 2023). The type species of lentivirus and the etiologic agent of acquired immunodeficiency syndrome (AIDS). "Recently, a higher level of SerpinA5 was observed in the cervicovaginal fluid in HIV-1-exposed seronegative individuals than that in HIV-1-exposed seropositive individuals, suggesting that SerpinA5 might be a protective factor when determining susceptibility to HIV-1 infection." (PMID 36982532, 2023). "Interestingly, a recent study showed that SerpinA5 might have a protective role against HIV-1 infection." (PMID 36982532, 2023).
Hodgkin’s disease (1 paper, 2020). "SERPINA5 was significantly overexpressed in testicular cancer, Hodgkin’s disease, and lymphoma groups, while SOD1 was underexpressed in leukemia and lymphoma cancer compared to fertile men." (PMID 32942548, 2020).
lung carcinoma (1 paper, 2018). "The association between SERPINA5 and this subtype of lung cancer is an inspiring result, but the expression status (at transcriptional or post-transcriptional level) and biological function of this gene in LUAD are largely unknown." (PMID 29713243, 2018).
male infertility (1 paper, 2019). The inability of the male to effect fertilization of an ovum after a specified period of unprotected intercourse. "Serpin family protein SERPINA5 is implicated in the fertilization process, as it inhibits the binding and penetration of sperm and plays a prominent role in male infertility." (PMID 30764484, 2019).
myocardial infarction (1 paper, 2022). Gross necrosis of the myocardium, as a result of interruption of the blood supply to the area, as in coronary thrombosis. "Elevated plasma concentrations of active SERPINA5 have been observed in survivors of myocardial infarction, and appear to represent a risk marker for acute coronary events." (PMID 35945262, 2022).
Neurofibrillary tangles (1 paper, 2021). Pathological protein aggregates formed by hyperphosphorylation of a microtubule-associated protein known as tau, causing it to aggregate in an insoluble form. "Given SERPINA5’s association with neurofibrillary tangle pathology and its predominantly neuronal expression, we hypothesized that SERPINA5 would follow the corticolimbic patterns inherent to each of the AD subtypes." (PMID 33875655, 2021).
renal carcinoma (1 paper, 2010). A carcinoma arising from the epithelium of the renal parenchyma or the renal pelvis. "SERPINA5, down-regulated in the cancer, regulates the invasive potential of renal cancer growth and invasion." (PMID 21060876, 2010).
serous carcinomas (1 paper, 2013). "The expression of SERPINA5 was found to be significantly reduced in advanced-stage serous ovarian borderline tumors and serous carcinomas when compared with the early-stage counterparts, and such a reduction was linked to more aggressive features of the ovarian borderline tumors." (PMID 23520464, 2013).
trisomy 21 (1 paper, 2025). A chromosomal disorder consisting of the presence of an extra chromosome 21. "Similarly, SERPINA5 and PLG mediate coagulation and fibrinolysis, while GSTM5 participates in oxidative stress defense—mechanisms often disturbed in chromosomal abnormalities and reported in trisomy 21 placentas." (PMID 41614738, 2025).
vasculitis (1 paper, 2023). "Overall, the high fold increases in MASP1 and CFB together with decreased SERPINA5 and increased C9 suggest the role of the lectin and alternate complement pathway in this form of vasculitis." (PMID 37238213, 2023).
viral infection (1 paper, 2023). "Based on these observations, we subsequently explored whether SerpinA5 could affect the outcome of virus infections in cell culture." (PMID 36982532, 2023). "Our results showed that SerpinA5 expression in BMM cells was significantly upregulated after the stimulation with TLR agonists and viral infections in a time-dependent manner." (PMID 36982532, 2023). "Mechanistically, SerpinA5 can upregulate the phosphorylation of STAT1 and promote its nuclear translocation, thus effectively activating the transcription of IFN-related signaling pathways to impair viral infections." (PMID 36982532, 2023). "So far, to our best knowledge, the roles of SerpinA5 in regulating innate immune signaling to control viral infection are not clarified." (PMID 36982532, 2023). "However, it is not clarified yet how SerpinA5 regulates the innate immune signaling against viral infections." (PMID 36982532, 2023). "In summary, we identified that SerpinA5 could exert a previously unrecognized function as a novel ISG with antiviral activity, and we also proposed a working model for the roles of SerpinA5 in regulating innate immune signaling to control viral infection." (PMID 36982532, 2023).
tumor (26 papers, 2012 to 2025). "The expression of CNV-deficient ARGs, including SERPINA5, was lower in tumor tissues than in normal colorectal tissues, indicating that CNV might regulate the expression of ARGs." (PMID 36909170, 2023). "It has been demonstrated that overexpression of SERPINA5 reduces metastasis, invasion, and angiogenesis of tumor cells." (PMID 39012409, 2024). "By contributing to a pro-thrombotic environment, SERPINA5 supports ccRCC progression and metastasis, aiding in the tumor’s ability to evade immune surveillance and promote aggressive behavior." (PMID 39348357, 2024). "According to reports SERPINA5 plays a protective function against tumor formation, invasiveness, and metastasis and is dysregulated in renal, breast, prostate, liver, and ovarian malignancies." (PMID 39348357, 2024). "SERPINA5 relates to male reproductive function and tumor suppression and has been found in the human reproductive tract, liver, and kidney." (PMID 38136662, 2023). "In this point, previous study suggested SERPINA5 regulates tumour invasion by inhibiting urokinase‐type plasminogen activator, but regulation tumour growth by SERPINA5 is not dependent on its protease inhibitory activity." (PMID 36000536, 2022). "This study showed that SERPINA5 has a high expression in GC, which is inconsistent with previous reports of SERPINA5 in other tumours." (PMID 36000536, 2022). "Due to the function of uPA in tumour cell metastasis and uPA is inhibited by SERPINA5,36, 37 SERPINA5 should be closely related to tumour metastasis, and there are indeed some studies that substantiate this point." (PMID 36000536, 2022). "We then examined the expression levels of SERPINA5 in GC tissues and corresponding non‐tumour tissues via qRT‐PCR." (PMID 36000536, 2022). "SERPINA5 plays important roles in tumours, including preventing metastasis and anti‐angiogenesis, since it engages in a wide range of biological activities, including inflammation." (PMID 36000536, 2022). "Previous studies also revealed that SerpinA5 might play a function in host defense, such as tumor suppression." (PMID 36982532, 2023). "SERPINA5 is an important component of the SERPIN family known as a putative tumour suppressor gene." (PMID 36831393, 2023). "Then, our series of experiments indicated that SERPINA5 promotes GC cells proliferation ability by inhibiting cell apoptosis and promoting cell cycle progression, which is completely different from that reported for SERPINA5 in other tumours." (PMID 36000536, 2022). "Furthermore, in vivo experiments and more in‐depth mechanism research are necessary to confirm the possibility of SERPINA5 in tumour therapy." (PMID 36000536, 2022). "According to the function related to inflammation, angiogenesis, apoptosis, fibrosis and tumor growth, which are closely associated with either the development of DR or VEGF signaling, we were interested in following candidate proteins: APOC1, SERPINA5, TIMP2, and KRT1." (PMID 29541006, 2018). "In addition, SerpinA5 might act as an antimicrobe agent and a tumor suppressor to negatively regulate tumor cell growth and metastasis." (PMID 36982532, 2023). "Notably, the product of SERPINA5 is known to inhibit activated protein C. This protein C inhibitor (PCI) plays a role in tumor growth and metastasis through its effect on blood coagulation, but it has also been suggested to inhibit the anti-inflammatory activity of activated protein C." (PMID 28270177, 2017). "The epithelial activation markers REG and SERPINA5, the interferon response marker MX1, and the anti-inflammatory protein IL1RN were found significantly deregulated in tumour tissue, similar to the inflamed tissue." (PMID 36961872, 2023). "While the comparison of expression data between tumor and normal samples showed that 8 out of 36 ARGs were significantly differentially expressed, including CCND2, CXCL6, KCNJ8, LPL, SERPINA5, SLCO2A1, VTN, and APOH." (PMID 35836112, 2022).
tumor (continued). "All three negative regulators, the endogenous protease inhibitors, demonstrated a trend for reduced mRNA expression in tumor tissues compared to normal, with SPINT1 and SERPINA5 having a reduction in mRNA expression that reached statistically significant levels." (PMID 38212428, 2024). "Additionally, SERPINA5 had differential expression in normal and metastatic tissues, while APP as well as OLR1 had differential expression in tumor and metastatic tissues (P < 0.05)." (PMID 39012409, 2024). "Notably, there was a positive association between the levels of ARGs and CNV alteration; for example, the expression levels of PRG2, SERPINA5, and THBD were low in tumor tissues, while VEGFA, PF4, and PTK2 were expressed at high levels." (PMID 37938164, 2023). "However, since SERPINA5 has only been reported in a few tumour types, and the heterogeneity among different tumour types, the previous results are not representative of the expression of SERPINA5 in all tumours." (PMID 36000536, 2022). "The second peak with the suggested protein, PCI (SerpinA5), is a component of the anticoagulant protein C pathway, originally identified in human plasma as an inhibitor of activated protein C. PCI also inhibits urinary plasminogen activator (uPA), which is a mediatior of tumor cell invasion." (PMID 23268721, 2012).
cancer (13 papers, 2010 to 2024). A tumor composed of atypical neoplastic, often pleomorphic cells that invade other tissues. "Furthermore, SERPINA5, the protein responsible for the binding and penetration of spermatozoa into the oocyte, was overexpressed in spermatozoa of men with all the cancer types, suggesting an impairment of fertilization-associated pathways." (PMID 32942548, 2020). "It is most mentioned that SERPINA5 plays a role in hemostasis, male fertility, and cancer protection." (PMID 36699448, 2022). "Previous reports showed that SERPINA5 exhibited low expression in a range of cancers, including renal, breast, prostate and ovarian tumours." (PMID 36000536, 2022). "Results show that SPARCL1, CDH2, CP, HP, TF and SERPINA5 were all significant downregulated in cancer tissues (p < 0.05)." (PMID 34422629, 2021). "Another cancer related gene discovered in our prognostic signature is SERPINA5, also called Protein C Inhibitor(PCI), belongs to the serine protease inhibitor super family as well." (PMID 29713243, 2018). "In addition, compared to liver metastatic cancer tissues, CP, HP, TF, and SERPINA5 were upregulated in normal liver tissues, while the expression CDH2 and SPARCL1 did not exhibit significant differences between the two tissues." (PMID 34422629, 2021). "Moreover, altered expression of proteins (NDUFS1, SOD1, SERPINA5, and UQCRC2) involved in sperm fertility potential and motility suggests that the fertility of cancer patients may be at risk due to the aberrant expression of critical sperm proteins." (PMID 32942548, 2020). "To learn more about the underlying mechanism, we tried to predict the potential interactors of SERPINA5, focusing initially on CBL, an E3 ubiquitin ligase of several tyrosine kinase receptors that functions as a suppressor gene in many cancers." (PMID 36000536, 2022).
infection (2 papers, 2017 to 2019). The state of being infected such as from the introduction of a foreign agent such as serum, vaccine, antigenic substance or organism. "Serpina5, Gzmd, Gzmg and Scgb1a1 are genes which transcription was negatively affected by the infection by both strains." (PMID 28273076, 2017).
SERPINA5 also shares sentences with these, for which no sentence is quoted: interstitial lung disease (2 papers); apical periodontitis (1); Cataplexy (1); Cirrhosis (1); coagulopathy (1); colorectal cancer (1); Ehlers-Danlos syndrome (1); glomerulosclerosis (1); Hallucinations (1); hypertriglyceridemia (1); Immunodeficiency (1); inflammatory bowel disease (1); leukemia (1); liver (1); lymphoma (1); malaria (1); Miscarriage (1); multiple sclerosis (1); osteoarthritis (1); Ovarian cyst (1); Parkinson disease (1); periodontitis (1); pulmonary edema (1); rectum adenocarcinoma (1); renal cell carcinoma (1); serous ovarian borderline tumors (1); Shock (1); testicular cancer (1); Thromboembolism (1); viral meningitis (1).
A further 1 disease shares a sentence with SERPINA5 in 1 paper.